CLOCK (clock circadian regulator)
Diseases named in the same sentence as CLOCK in open-access papers (continued):
Sharing a sentence is not in itself a finding about the gene and the disease.
tumor (continued). "Under the circumstance that CLOCK and BMAL1 are lower expressed, the tumor microenvironment is in the state of “nighttime”." (PMID 31881010, 2019). "In addition, the myelocytomatosis oncogene cellular homolog (Myc) proto-oncogene is thought to be regulated by BMAL1/neuronal PAS domain protein 2 (NPAS2) (a CLOCK paralogue) action on its E-boxes, which may contribute to enhanced tumor growth in Per2 mutant mice in response to DNA damage." (PMID 31039152, 2019). "In this study, we demonstrate for the first time that CLOCK and BMAL1 promote cytoskeletal F-actin filament formation by regulating the RHOA-ROCK-CFL pathway, revealing a novel mechanism of circadian genes in tumor cells." (PMID 30287810, 2018). "Considering that F-actin filament dynamics are involved in a variety of significant bioprocesses, our current research provides a new perspective on the roles of CLOCK and BMAL1 in tumor cells." (PMID 30287810, 2018). "PER1, PER2, PER3, CRY2 were found to be significantly down-expressed, while CLOCK, TIMELESS were over-expressed in the studied tumor samples compared to the non-tumor samples." (PMID 29958276, 2018). "In conclusion, our research proposes a novel insight into the role of CLOCK and BMAL1 in tumor cells." (PMID 30287810, 2018). "The CLOCK protein, which also exhibits HAT activity, seems to have tumor-promoting properties and to favor cell proliferation." (PMID 25310649, 2014). "Other studies suggested depletion of core genes CLOCK and BMAL1 impairing tumor progression." (PMID 40565338, 2025). "Accordingly, researchers have begun to investigate the links between circadian disruption and oncogenesis, such as the tumor-suppressor roles of BMAL1 and PER2 in lung tumor initiation and progression, and the induction of MYC by CLOCK and bHLH proteins, which facilitates neuroblastoma progression." (PMID 40700255, 2025). "Dual targeting macrophages and microglia via inhibition of LOX and the CLOCK-OLFML3 axis generates potent antitumor effects and offers a complete tumor regression in more than 60% of animals when combined with anti-PD1 therapy in PTEN-deficient GBM mouse models." (PMID 39352749, 2024). "CLOCK might interact with HIF-1α/ Bmal1 and activate VEGF to stimulate tumor angiogenesis and metastasis." (PMID 32437452, 2020). "We only observed higher CLOCK expression in the tumor tissue samples in comparison with the non-tumor adjacent tissue samples." (PMID 29958276, 2018). "However, the roles of the CLOCK and BMAL1 genes in the regulation of tumor progression via the RHOA-ROCK-CFL pathway remain largely unclear." (PMID 30287810, 2018). "CLOCK was significantly reduced in the tumour cells, but not in the nucleus or cytoplasm in the neighbouring mucosa." (PMID 27465361, 2016). "Due to the obscure tumor grades recorded for some of the specimens, it was not possible to establish a correlation between CLOCK expression and tumor grades." (PMID 24789043, 2014). "Additional findings suggest that the master regulators CLOCK and BMAL1 possess anti-apoptotic functions that contribute to the proliferation of liver cancer cells, while their inhibition leads to dysregulation of WEE1 and p21, ultimately promoting tumor cell death." (PMID 40700255, 2025). "Dysregulation of circadian rhythm genes—such as CLOCK, BMAL1, PER, and CRY—may result in abnormal proliferation, metabolic reprogramming, genomic instability, immune evasion, and microenvironmental remodeling in HCC cells, thereby promoting tumor progression." (PMID 41298718, 2025). "In particular, it has been demonstrated that overexpression of CLOCK enhances the expression of genes related to angiogenesis, including vascular endothelial growth factor (VEGF), hypoxia-inducible factor 1-alpha, (HIF1α), and basic helix-loop-helix (BMAL1), which is a tumor suppressor." (PMID 38892035, 2024). "However, depending on the model and the tissue, CLOCK and BMAL1 may be oncogenic or tumor suppressive." (PMID 33810377, 2021).
tumor (continued). "Thus, to examine whether CLOCK and BMAL1 can promote tumor cell proliferation via RHOA, the Cell Counting Kit-8 assays were introduced to observe cell proliferation in HeLa cells." (PMID 30287810, 2018). "Similar to the survival benefits induced by LOX inhibition, we found that CLOCK inhibition using SR9009 combined with anti-PD1 therapy resulted in survival extension, but did not cure any tumor-bearing mice, in CT2A and 005 GSC models." (PMID 39352749, 2024). "Moreover, the mRNA expression of CLOCK, CRY1, and CRY2 declined in tumor tissues compared with normal tissues (p < 0.001)." (PMID 32681792, 2020). "However, our previous study indicated that the expression of CLOCK and BMAL1 demonstrate no circadian rhythmicity in tumor cells." (PMID 30287810, 2018).
metabolic disorders (13 papers, 2016 to 2025). "Another circadian clock protein PER2 inhibits the expression of PAI-1 in a CLOCK/BMAL1-dependent manner as an important factor in the development of these metabolic diseases after the circadian clock system is dysregulated." (PMID 34566581, 2021). "In humans, like mice, polymorphisms of CLOCK and BMAL1 have been associated with metabolic disorders." (PMID 28977444, 2017). "In addition, SNPs in CLOCK : BMAL1-repressing genes, such as Cry and Per genes, have also been implicated in metabolic disease." (PMID 36034454, 2022).
cardiovascular diseases (12 papers, 2011 to 2024). "A number of studies reported that mutations in core circadian gene BMAL1 or its partner CLOCK tended to develop cardiovascular diseases." (PMID 32277346, 2020). "Especially, mutations in BMAL1 or its partner CLOCK could lead to cardiovascular disease." (PMID 35996077, 2022). "Genetic variations in the CLOCK gene are connected with blood pressure and cardiovascular disorders in humans." (PMID 34066863, 2021). "Mediterranean diet has shown positive effects on cardiovascular diseases, through the modulation of different gene expression, such as the following: the circadian locomotor output cycle protein kaput (CLOCK) gene related with glucose metabolism and NF-κB related with inflammation." (PMID 35059043, 2022). "Since PAI-1 expression peaks at 6 am, and it has been shown that CLOCK/BMAL1 heterodimer induced activation of the Serpine1 promoter through E-box, this may lead to an increased risk of cardiovascular disorders during early morning hours." (PMID 34014841, 2021). "Genetic variations in the CLOCK gene are connected with T2DM and cardiovascular disorders in humans." (PMID 32050674, 2020).
psychiatric disorder (12 papers, 2016 to 2025). A disorder characterized by behavioral and/or psychological abnormalities, often accompanied by physical symptoms. "CLOCK variants have been found to be associated with a wide array of psychiatric disorders, but the clinical significance of these associations still remains undefined." (PMID 37761843, 2023). "Taylor and Hasler also concluded that specific genes associated with chronotypes and psychiatric disorders include CLOCK, PER3, ARNTL, and TIM." (PMID 38124075, 2023). "In previous studies, different researchers have found that the polymorphism of CLOCK 3111T/C is associated with psychiatric disorders." (PMID 29535854, 2018). "However, CLOCK 3111T/C SNP has been associated with the recurrence of unfavorable sleep phenotypes in patients diagnosed with different psychiatric disorders." (PMID 37761843, 2023). "Mutations of the CLOCK gene have been implicated in many psychiatric disorders." (PMID 35237186, 2022). "Finally, in humans, an association between the CLOCK gene and psychiatric disorders has already been reported." (PMID 30696097, 2019). "For instance, in other psychiatric disorders, where the CLOCK gene is more explored, ancestry seems to be an important factor in understanding the mixed results." (PMID 30696097, 2019).
infection (4 papers, 2015 to 2023). The state of being infected such as from the introduction of a foreign agent such as serum, vaccine, antigenic substance or organism. "The effect of the circadian clock on the infection outcome is also investigated through silencing of the CLOCK gene that is central in the regulation of animal circadian rhythms." (PMID 36454885, 2022). "Infection of mice with Salmonella typhimurium during their rest phase, for example, resulted in higher bacterial loads compared with those infected in the middle of the active phase, and this is CLOCK-dependent." (PMID 36275731, 2022). "We found that treatment with the circadian-enhancing agents nobiletin and SR8278 reduced infection of herpes simplex virus 1 in epidermal explants and human keratinocytes in a BMAL1/CLOCK-dependent manner." (PMID 37725438, 2023).
heart disease (2 papers, 2010 to 2019). "To test this, we focused on the circadian factor CLOCK, as it is a canonical part of the circadian mechanism, and relatively well characterized in experimental heart disease models." (PMID 30899044, 2019). "In doing so, CLOCK regulates daily patterns of genes and proteins in the normal heart, and cardiac remodeling in heart disease (e.g.10,16,21,22,37)." (PMID 30899044, 2019).
hematologic malignancy (1 paper, 2023). "As CLOCK is known to be associated with the lymphocyte survival/recovery rate, investigating its link with the sex-specific chronotherapeutic effect in hematologic malignancy would be interesting for future work." (PMID 36512421, 2023).
vascular disorder (1 paper, 2025). A general term used to describe any disease affecting blood vessels]. "Alterations of CLOCK, Bmal1, PER1, and PER2 has been observed in the placental cells of pregnant women with vascular disorders like pre-eclampsia." (PMID 40137423, 2025).
CLOCK also shares sentences with these, for which no sentence is quoted: anxiety disorder (3 papers); Sleep disturbance (3); autism spectrum disorder (2); chronic lymphocytic leukemia (2); chronic obstructive pulmonary disease (2); head and neck squamous cell carcinoma (2); renal cell carcinoma (2); acute myocardial infarction (1); alcohol (1); alcohol abuse (1); allergic asthma (1); allergic contact dermatitis (1); Allergy (1); atopic dermatitis (1); brain cancer (1); brain disorder (1); chronic myelogenous leukemia, BCR-ABL1 positive (1); cognitive decline (1); cognitive disorder (1); diabetic nephropathy (1); disc degeneration (1); dysthymia (1); endometriosis (1); esophageal cancer (1); fibrosis (1); gastrointestinal disease (1); Hyperinsulinemia (1); Hypoinsulinemia (1); Impaired glucose tolerance (1); infarction (1).
A further 25 diseases each share a sentence with CLOCK in 1 paper.